TCEAL2 (transcription elongation factor A like 2)
Description:
May be involved in transcriptional regulation.
Synonyms: My048; MY0876G05; WEX1
Tractability: PROTAC: ubiquitination databases record sites on it.
Gene: Protein-coding gene on chromosome X (102,125,130 to 102,140,426, forward strand). Ensembl gene ENSG00000184905.
Subcellular location: Nucleus
Subcellular location (Human Protein Atlas): Nuclear speckles; Cytosol
Gene Ontology:
Cellular component: nucleus
Homologues: Orthologues: macaque TCEAL2 (92% identical), pig TCEAL2 (65% identical), dog TCEAL4 (63% identical). Paralogues in human: TCEAL4 (78% identical), TCEAL5 (43% identical), TCEAL3 (42% identical), TCEAL6 (41% identical), TCEAL1 (17% identical), TCEAL8 (17% identical), TCEAL9 (16% identical), TCEAL7 (12% identical).
Diseases named in the same sentence as TCEAL2 in open-access papers:
TCEAL2 is named in the same sentence as 10 diseases in open-access papers, as found by Europe PMC text mining. Sharing a sentence is not in itself a finding about the gene and the disease. The quoted sentences say what the papers report.
ovarian carcinoma (2 papers, 2020 to 2022). A malignant neoplasm originating from the surface ovarian epithelium. "Several studies have observed that TCEAL2 was overexpressed in various tumors including meningioma and ovarian carcinoma, and it was closely related to poor clinical outcome." (PMID 35421923, 2022).
breast carcinoma (1 paper, 2022). "Since TCEAL2 and MBNL1 have been reported to be potential therapeutic targets in SCLC and breast cancer respectively, their translation values in GC are worthy of further investigation." (PMID 35421923, 2022).
gastric cancer (1 paper, 2022). A primary or metastatic malignant neoplasm involving the stomach. "Eventually, TCEAL2 and MBNL1 were proved to be differentially regulated by CREB1 during tumorigenesis of gastric cancer." (PMID 35421923, 2022). "We therefore proposed TCEAL2 and MBNL1 as potential therapeutic targets for gastric cancer." (PMID 35421923, 2022).
serous ovarian cancer (1 paper, 2020). "Whereas TCEAL2 up-regulation was reported to associate with poor prognosis for serous ovarian cancer patients, TCEAL-1, 4, and 7 were reported to be down-regulated in different tumour types." (PMID 33033111, 2020).
cancer (2 papers, 2022 to 2025). A tumor composed of atypical neoplastic, often pleomorphic cells that invade other tissues. "The overexpression of TCEAL2 in cancer condition was observed in our GSE54129 dataset, meanwhile the loss of negative regulation of TCEAL2 by CREB1 in cancer was inferred, which may facilitate proliferation and inhibit apoptosis and thus promotes carcinogenesis." (PMID 35421923, 2022). "For the remaining genes in this set, namely TCEAL2, SYNM, and DES, direct validation of their functional roles in different cancers remains to be done." (PMID 41439026, 2025). "According to the regulation efficacy data, the positive regulation of TRIM15 and NHERF1 by CREB1 was reversed from normal to cancer; the negative regulations of TCEAL2, RBPMS2 and FAM20C by CREB1 disappeared; and the negative regulation of FERMT2 was reversed from normal to cancer." (PMID 35421923, 2022). "Though TCEAL2 is not a known GC-related gene, it was reported to be a potential immunotherapeutic target in SCLC and could be involved in promoting proliferation and inhabiting apoptosis of cancer cells." (PMID 35421923, 2022).
TCEAL2 also shares sentences with these, for which no sentence is quoted: tumor (2 papers); clear cell renal cell carcinoma (1); meningioma (1); metastatic tumors (1); renal cell carcinoma (1).